PPARG (peroxisome proliferator activated receptor gamma)
Diseases named in the same sentence as PPARG in open-access papers (continued):
Sharing a sentence is not in itself a finding about the gene and the disease.
cancer (continued). "In brief, liver inflammation and cancer caused by HBx-induced activation of CDC42 and PPARγ, and followed by disruption of cytoskeleton and lipid metabolism." (PMID 27708241, 2016). "Increased level of PPARγ in carcinomas can stimulate angiogenesis through up-regulation VEGF or other pro-angiogenic factors." (PMID 26814431, 2016). "Together, our findings demonstrate potential utility of manipulating miR-27b levels in cardiovascular disease and cancer and confirm its targets as Dll4/Notch axis, PPARγ and its downstream effectors." (PMID 26161255, 2015). "PPARγ expression compared to normal tissue tends to be increased in precursor lesions and differentiated tumors and decreased in the poorly differentiated cancers." (PMID 25866814, 2015). "Following administration of DMBA, the incidences of cancer and metastasis in PPARγ heterogenous knockout mice were ≥3-fold and 4.6-fold those in PPARγ wild mice, respectively." (PMID 25734181, 2015). "Numerous studies have shown that PPARγ agonists influence broad biological processes, including cancer." (PMID 26091518, 2015). "Apart from the established metabolic actions, PPARγ also plays a key role in multiple types of cancer, including lung, colon, breast, prostate, pancreas and bladder." (PMID 26184238, 2015). "The activation of PPARγ plays an inhibitory role in cellular proliferation and growth, this property makes PPARγ an important target for the development of new drugs aimed at preventing and treating cancer." (PMID 26184238, 2015). "Numerous studies have tested the effects of different agonists of PPARγ in cancer cell lines and erythropoiesis." (PMID 25870831, 2015). "One other notable NR that trended toward higher expression in the metastasis-derived uveal lines was PPARg, which has been noted in many cancer models to be anti-proliferative upon ligand activation." (PMID 26217306, 2015). "Taken together, these studies suggest that PSF is a regulator of cell death in some cancer cells and that the relative expression level of PPARγ appears to play an important role in mediating cell death." (PMID 26309807, 2015). "Although a main role of PPARγ has been shown in the adipocyte differentiation and insulin sensitisation, PPARγ is also well-known to affect growth and cell cycle, differentiation and apoptosis of various types of cancer cells including colon." (PMID 26492315, 2015). "For this reason, and in consideration of the significant efficacy of both rosiglitazone and pioglitazone as inhibitors of oral carcinogenesis, PPARγ remains a potentially valuable molecular target for cancer chemoprevention in the oral cavity and other sites." (PMID 26516762, 2015). "Is has previously been reported that the in vitro anti-cancer effects of 9Z11E-LA and 10E12Z-LA isomers involve numerous pathways, including PPARγ, CAR or ERα pathway." (PMID 25844926, 2015). "Consistent with our observations, other animal models of cancer cachexia exhibit impaired lipogenesis through reduced PPARγ action during cancer cachexia." (PMID 24667661, 2014). "Δ2TG, a PPARγ-inactive analogue of TG, was modestly more potent than their parent compounds in suppressing cell proliferation in cancer cells." (PMID 25328285, 2014). "Ceramide mediates inhibition of cyclooxygenase-2 (COX-2) which catalyzes formation of prostaglandin further activating peroxisome proliferator-activated receptorγ (PPARγ) and Wnt/β-catenin pathway; and hence plays a critical role in cancer." (PMID 24999478, 2014). "The results of an elevated PPARγ in postinitiation phase in the current study are contrary to other reports which have revealed a decreased expression of PPARγ in cancer." (PMID 24999478, 2014). "In prior studies, PPARγ activation led to apoptosis and cell cycle inhibition in various cancer cells." (PMID 25360175, 2014).
cancer (continued). "The authors cited disruption of SDF-1/CXCR4 signaling in the metastasis of stem-like cancer cells by a PPARγ dependent mechanism as a possible new cancer control treatment." (PMID 25191225, 2014). "The effectiveness of PPARγ agonists as anticancer agents has been examined in various cancers including colon, breast, lung, ovary and prostate." (PMID 25119466, 2014). "PPARγ agonists induce p38 activation, leading to apoptosis of cancer cells have been reported in chondrocytes, human lung cells, liver epithelial cells and skeletal muscle." (PMID 25119466, 2014). "The cell death inducing effect of high doses of PPARγ antagonists led to discuss them as potential therapeutic agents in the treatment of cancer but must be considered undesired in primary cells." (PMID 25054074, 2014). "Together these results suggest that the PTER-ITC conjugate acts as a PPARγ agonist and is a promising candidate for cancer therapy, alone or in combination with existing therapies." (PMID 25119466, 2014). "Thiazolidinediones (TZDs), synthetic peroxisome proliferator-activated receptor gamma (PPARγ) ligands, suppress cancer cell proliferation through the interplay between apoptosis and autophagy." (PMID 24924771, 2014). "It thus appears that PPARγ activation or inhibition can have distinct roles in tumorigenesis, depending on the cancer model examined." (PMID 25119466, 2014). "The expression of PPARγ and the effects of PPARγ ligands on cell growth have been extensively studied in many carcinoma cell types including lung." (PMID 24925061, 2014). "It has been shown that TZDs suppress the growth of several cancer lines in vitro and in vivo, and lines of preclinical evidence supports the antineoplstic effects of PPARγ agonists; however, results from clinical trials show modest success." (PMID 23614038, 2013). "Some studies have identified EPA and DHA as ligands of peroxisome proliferator-activated receptors gamma (PPARγ), nuclear factor kappa B, and retinoid X receptors, which have anti-inflammatory effects as well as antiproliferative effects in cancer cells." (PMID 23589776, 2013). "In a study of the Danish Diet, Cancer and Health cohort, interaction between PPARG Pro12Ala and alcohol intake was found." (PMID 23216531, 2013). "The transcription factors peroxisome proliferator-activated receptor γ (PPARγ) and activating protein 2 (aP2), are involved in the adipogenic differentiation of hADSCs and the occurrence, progression and prognosis of cancer." (PMID 24137293, 2013). "PPARγ agonists have also been shown to arrest cell proliferation, induce apoptosis, decrease cell adhesion and migration, and promote differentiation of cancer cells of different origins." (PMID 24023668, 2013). "Many of these PPARγ agonists exhibit antiproliferative activities against many types of cancer cells including those of colon, prostate, and breast, suggesting the potential use of these agents in cancer therapy or prevention." (PMID 23843889, 2013). "Recently, several studies reported that PPARγ agonists inhibit cancer cell proliferation, survival, and invasion." (PMID 23476786, 2013). "LPA is a PPARγ agonist that induces cell proliferation and invasion, but cPA exerts the opposite effects in cancer cells." (PMID 23476786, 2013). "POX is up-regulated by oxidized low-density lipoproteins through peroxisome proliferator-activated receptor gamma and plays a key role in the regulation of protective autophagy in cancer cells." (PMID 24039956, 2013). "Peroxisome proliferator-activated receptor gamma (PPARγ) plays critical roles in lipid storage, glucose metabolism, energy homeostasis, adipocyte differentiation, inflammation, and cancer." (PMID 22848209, 2012). "Although the involvement of PPARγ in the development of cancer in various tissues remains controversial, PPARγ activation has antitumorigenic effects due to its antiproliferative and prodifferentiation activities." (PMID 22936949, 2012).
cancer (continued). "The high cytoplasmic-to-nuclear expression ratio of PPARγ decreases as the differentiation stage changes from IM to adenoma, and to well-, moderately-, and poorly-differentiated cancers." (PMID 22936949, 2012). "For example, CDDO, CDDO-Me, and CDDO-Im activate PPARγ-dependent and -independent pathways that inhibit cancer-cell growth." (PMID 22685453, 2012). "Although increasing evidence has established that PPARγ agonist induces growth arrest in cancer cells, the molecular mechanism of the growth inhibition by PPARγ agonist is not well understood and complicated." (PMID 23024650, 2012). "PPARγ also remains a potential target for the treatment and prevention of cancer, in particular for PPARγ agonists with good safety profiles." (PMID 22966221, 2012). "In this paper, we take a comprehensive look at the current understanding of the relationship between PPARγ and cancer development." (PMID 22848209, 2012). "Similar to PPARγ, RXRα activation profoundly affects multiple cellular activities that are pertinent to cancer including cellular growth, differentiation, apoptosis, and morphogenesis." (PMID 22966225, 2012). "The metabolic and anti-inflammatory properties of PPARγ, along with its role in cell differentiation, have encouraged to pursue for new functions in cancer." (PMID 22848209, 2012). "In mice with cancer cachexia, the PPARγ (PPARG) agonist rosiglitazone, an insulin sensitizer, increases adipose tissue but not muscle mass in late-stage cachexia." (PMID 23781298, 2012). "Activation of PPARγ in a variety of cancer cells leads to inhibition of growth, decreased invasiveness, reduced production of proinflammatory cytokines, and promotion of a more differentiated phenotype." (PMID 22934105, 2012). "Although PPARγ activators have been proven to contribute to anticancer actions during many in vitro studies, their advancement into human cancer clinical trials has met with limited success." (PMID 23213321, 2012). "PPARγ has been known to be related to inflammation, immune response, and pathogenesis of some disorders including obesity, atherosclerosis, cancer, and so on." (PMID 23024650, 2012). "Currently, because of the antitumor and antiangiogenic properties as well as the low toxicity profile, the TZD members have been tested in clinical trials for treatment of human cancers expressing high levels of PPARγ." (PMID 23213321, 2012). "We will provide an overview of the current findings on PPARγ activation and the targeting in prostate carcinogenesis prevention with the respect of applying PPARγ activators as cancer chemoprevention strategies." (PMID 23213321, 2012). "It has been demonstrated that PPARγ agonists affect these parameters not only in the control of cell inflammation but also in several types of cancer cells." (PMID 22761953, 2012). "PPARγ is expressed in a variety of tumors and its role in cancer formation/progression has been controversial for long time." (PMID 22848209, 2012). "The PPARγ activation by agonists regulates lipid storage in adypocytes, inhibits proliferation and induces differentiation and apoptosis in a number of cancer cells." (PMID 22761953, 2012). "The PPARγ target genes that mediate the antiproliferative effects remain also elusive, as genomic responses to PPARγ activation in cancer cells are highly complicated." (PMID 22808264, 2012). "PPARγ activation by its ligands can induce growth arrest, differentiation, and apoptosis of cancer cells." (PMID 22693486, 2012). "In vitro studies have shown that PPARγ activation results in growth arrest of epithelial-derived cancer cell lines, including those from thyroid, lung, prostate, breast, pituitary, and colon." (PMID 22848209, 2012). "Of the three PPARs identified to now, PPARγ represents the most promising target in view of the many reports implicating this molecule in cancer cell growth." (PMID 23024650, 2012).
cancer (continued). "A strategy to address this issue is the use of molecular approaches, either by overexpressing or silencing PPARγ in cancer cells to complement studies with pharmacological agents." (PMID 22934105, 2012). "The overexpression of PPARγ inhibits the metastasis of carcinoma by increasing E-cadherin through TIMP3." (PMID 23316217, 2012). "We have shown that 15d-PGJ2 induces apoptosis in different cancer cells through PPARγ-independent NF-κB and caspase-dependent pathways, as also shown by other studies." (PMID 21957481, 2011). "Activation of peroxisome proliferator-activated receptor-γ (PPARγ) inhibits growth of cancer cells including non-small cell lung cancer (NSCLC)." (PMID 22145026, 2011). "In the present study, we have demonstrated the effects of 15d-PGJ2, a product of cyclo-oxygenase activity and as an endogenous PPARγ agonist, on apoptosis, drug resistance, cell migration and transformation of cancer cells." (PMID 21957481, 2011). "The presumed target of TZDs, PPARγ, is overexpressed in a variety of cancers including breast, lung, colon, prostate and ovary." (PMID 21283708, 2011). "The most striking finding was the correlation of PPARγ levels with the cancer origin (DTC versus ATC)." (PMID 22194735, 2011). "In all cases the fatty acid was capable of significantly ameliorating the disease via PPARγ-dependent responses such as induced apoptosis of cancer cells and reduced lipid storage during differentiation." (PMID 21904603, 2011). "PPARγ is predominantly found in normal adipose tissue, but is also expressed in cancer cells developed in a variety of tissues, including colorectum, breast, prostate, and tongue." (PMID 22174613, 2011). "This is supported by extensive studies demonstrating the effects of PPARγ activation in cancer cells on inhibition of transformed growth, induction of apoptosis, and promotion of differentiation." (PMID 22145026, 2011). "15-delta prostaglandin J2 has been shown to demonstrate inhibition of cell proliferation in cancers by peroxisome proliferator-activated receptor-gamma-dependent and -independent mechanisms." (PMID 21305029, 2011). "In co-culture experiments of cancer cells with bone marrow-derived macrophages, pioglitazone promoted arginase I expression in macrophages and this was dependent on the expression of PPARγ in the macrophages." (PMID 22145026, 2011). "Peroxisome Proliferator Activated Receptor gamma (PPARγ) agonists, such as the thiazolinediones (TZDs), have been studied for their potential use as cancer therapeutic agents." (PMID 21283708, 2011). "Inflammatory pathways involving PPARγ or COX-2 are promising therapeutic targets in a number of cancers." (PMID 21159167, 2010). "Many human cancer cell lines express high levels of PPARγ, which when treated with high concentrations of TZDs, undergo cell cycle arrest, apoptosis, or differentiation, suggesting a link between PPARγ signaling and their antitumor activities." (PMID 20204067, 2010). "Ligands of Peroxisome proliferator-activated receptor gamma (PPARγ) can inhibit growth and promote apoptosis in various cancer cells, and thus have the potential to be utilized as anticancer drugs." (PMID 21144036, 2010). "In terms of the cellular effects mediated by PPARγ in cancer cells, its role on growth arrest has been fairly well established, while significant controversy still exist regarding its role in mediating apoptosis." (PMID 21144036, 2010). "PPARγ agonists inhibit cancer growth by molecular mechanisms that include G1 cell cycle arrest, induction of apoptosis and terminal differentiation." (PMID 21129193, 2010). "Several lines of evidence indicate the presence of PPARγ-independent growth inhibition in some cancer types." (PMID 20170548, 2010). "Because peroxisome proliferator-activated receptor (PPAR)-γ agonists are potent mediators of anti-inflammatory responses, it was a logical extension to examine the role of PPARγ agonists in the treatment and prevention of cancer." (PMID 20204067, 2010).
cancer (continued). "Using a PPARγ antagonist (GW9662) and siRNA of PPARγ in poorly differentiated cancer cells, the authors showed a blunting of promoter activity, antiproliferative activity and p21WAF1/CIP1 up-regulation by PPARγ activation." (PMID 19267912, 2009). "xav mutants and MADD fibroblasts exhibit increased aerobic glycolysis, similar to the Warburg effect observed in cancer cells, leading to excessive neural proliferation in xav, mediated by upregulation of the PPARG-ERK pathway." (PMID 20020044, 2009). "The expression of PPARG in the cancer, however, can indicate a higher probability to respond to stroma-targeted approaches also without drugs aiming on PPAR." (PMID 19639032, 2009). "This agent is probably the most potent endogenous PPARγ ligand and has been widely used to study the role of PPARγ activation in cancer cells." (PMID 19884989, 2009). "The insulin sensitizing thiazolidinedione drugs, which are high affinity PPARγ agonists, are used to treat type 2 diabetes and experimentally to treat cancer." (PMID 19756148, 2009). "PPARG is a known regulator of the cell cycle and apoptosis, and is highly expressed in many cells, including neurons and some human cancer cells." (PMID 20020044, 2009). "Many in vitro studies have showed that ligand-induced activation of PPARγ possess antitumor effect in many cancers including CRC." (PMID 19884989, 2009). "Although central role of PPAR-γ has been demonstrated in the differentiation of adipose cells, PPARγ has also been shown to regulate the growth, differentiation, and gene expression in number of different cancer cells." (PMID 19356226, 2009). "Activation of the peroxisome proliferator-activated receptor-γ (PPARγ) has been identified as an approach to induce differentiation and inhibit proliferation in a variety of cancer cells." (PMID 19958503, 2009). "The role of the PPARγ isotype in cancer has been widely studied witha large number of reports demonstrating antitumoral properties of PPARγ agonists in a variety of different malignancies." (PMID 18670614, 2008). "Section 1 contains reviews that offer a comprehensive overview on PPARs' effects in cancer and on the more established role of PPARγ in cancer therapy." (PMID 19590598, 2008). "Given the fact that cancer cell migration and invasion are highly complex processes, the mechanism(s) by which PPARγ agonists exert theirantimigratory and anti-invasive properties requires further investigation." (PMID 18815619, 2008). "Pharmacological manipulation of TGFβ1 by PPARγ activators can be applied for treating TGFβ1-induced pathophysiologic disorders such as cancer metastasis and fibrosis." (PMID 18615188, 2008). "Multiple PPARγ-independentanticancer targets of PPARγagonists have been suggested in several cancer cell types." (PMID 18615188, 2008). "At the cellular level, PPARγ was found to be involved in cancer cellsurvival/apoptosis, proliferation, and differentiation." (PMID 18784849, 2008). "One of these reviews focuses on PPARγ, which historically has been studied most intensely in conjunction with cancer." (PMID 19590598, 2008). "PPARγ antagonist compounds have alsobeen shown to affect cell shape, adhesion, and invasiveness of cancer celllines." (PMID 18779871, 2008). "Although in the text, the vast majority of available data dealswith PPARγ agonists, some authors analyzedthe effect of PPARγ inhibitors on cancer cell growth." (PMID 18509497, 2008). "Based on the clinical experience todate, use of PPARγ agonists in cancer therapy will likely requirea targeted approach, with restriction to specific types of malignancies and/orstage(s) of disease susceptible to enhanced PPARγ signaling." (PMID 19125177, 2008). "One of the firststudies to analyze PPARγ status in an in vivo cancer setting examined 55 unrelated sporadic coloncancer samples and revealed 4 PPARγ mutations.Moreover, these mutations produced an inactive PPARγ protein." (PMID 19096712, 2008).